ANKRD11 (ankyrin repeat domain 11)
Diseases named in the same sentence as ANKRD11 in open-access papers (continued):
Sharing a sentence is not in itself a finding about the gene and the disease.
breast carcinoma (8 papers, 2009 to 2024). "The ANKRD11 gene locus is located within the 16q24.3 breast cancer loss of heterozygosity (LOH) region." (PMID 23718802, 2013). "However, in breast cancer, the expression of ANKRD11 is aberrantly downregulated, resulting in the pathogenic proliferation of tumor cells." (PMID 38115701, 2023). "Furthermore, higher expression of ANKRD11 was associated with poor prognosis in luminal A subtype of ER+ breast cancer but opposite outcome in ER− subset, implying a role of ANKRD11 in mediating resistance to endocrine therapies in ER+ breast cancer." (PMID 37414914, 2023). "In conclusion, the bioinformatic and experimental analyses suggest that ANKRD11 works downstream of ERα-SERPINA3 pathway to promote estrogen-deprivation-resistance (AI resistance) in ER+ breast cancer." (PMID 37414914, 2023). "One possible candidate gene involved in early-stage breast cancer progression is the ankyrin repeat domain containing 11 (ANKRD11/ANCO1)." (PMID 37511268, 2023). "Site-specific methylation was previously cited as the mechanism behind hTERT and ANKRD11 repression in colorectal carcinoma and breast cancer, respectively." (PMID 28077797, 2017). "In addition, according to TCGA data, high expression of ANKRD11 predicts worse prognosis in luminal A breast cancer but opposite outcome in luminal B and ER− subtypes which possess higher level of Ki67." (PMID 37414914, 2023). "More importantly, our findings suggest that decreased SERPINA3 as well as increased ANKRD11 expression as biomarkers that may predict the efficiency of HDAC3 inhibitor in treating AI-resistant breast cancer." (PMID 37414914, 2023). "This study provides the rationale to investigate whether effective HDAC3 inhibitors can improve the anti-tumor activities of AIs in endocrine-resistant breast cancer patients with upregulated ANKRD11 expression." (PMID 37414914, 2023). "By utilizing the two AI-resistant cell model MCF-7 LTED and T47D LTED, we revealed that downregulated expression of SERPINA3, an ERα target gene, confers endocrine-resistance to breast cancer cells during AI therapy by enhancing ANKRD11 expression and HDAC3 deacetylase activity." (PMID 37414914, 2023). "ANKRD11 expression was shown to be downregulated in breast cancer cell lines." (PMID 34604130, 2021). "Initially, ANKRD11 has been recognized as a tumor suppressor gene in breast cancer due to its location within the chromosomal region 16q24.3, which is widely acknowledged for its frequent loss of heterozygosity (LOH) among patients suffering from breast cancer." (PMID 39135054, 2024). "The distinguished roles of ANKRD11 in Ki67-high and -low group suggest a strong disturbance of Ki67 related pathway to ANKRD11 function and highlight the necessity of restrictive administration of HDAC3 inhibitor in luminal A breast cancer." (PMID 37414914, 2023). "In this study, SERPINA3 was identified to be a direct target gene of ERα, and its downregulation enhanced the expression of ankyrin repeat domain containing 11 (ANKRD11), which resulted in elevated HDAC3 activity and AI resistance in ER+ breast cancer." (PMID 37414914, 2023).
Cognitive impairment (5 papers, 2020 to 2025). Abnormal cognition is characterized by deficits in thinking, reasoning, or remembering. "Microdeletion of 16q24.3 is associated with ASD because it affects ankyrin repeat domain 11 (ANKRD11) and zinc finger protein 778 (ZNF778) genes, leading to cognitive impairment and brain abnormality." (PMID 32244359, 2020). "ANKRD11 gene deletion has also been reported in ASD and variable cognitive impairment in the absence of a syndromic presentation as well as in subjects with less specific KBG-like phenotypes." (PMID 32604767, 2020).
Kabuki syndrome (3 papers, 2019 to 2023). Kabuki syndrome (KS) is a multiple congenital anomaly syndrome characterized by typical facial features, skeletal anomalies, mild to moderate intellectual disability and postnatal growth deficiency. "Furthermore, one patient with KGB syndrome and Kabuki syndrome has been reported to have a de novo missense mutation of KDM1A, along with a de novo 3-bp deletion of another gene, ANKRD11." (PMID 31649809, 2019).
Obesity (3 papers, 2017 to 2022). Accumulation of substantial excess body fat.
epilepsy (2 papers, 2017 to 2023). A brain disorder characterized by episodes of abnormally increased neuronal discharge resulting in transient episodes of sensory or motor neurological dysfunction, or psychic dysfunction. "All patients with a likely pathogenic or pathogenic ANKRD11 variant were included in our patient cohort and categorized into an “epilepsy group” or “non‐epilepsy group”." (PMID 37501353, 2023). "Our aim is to describe the epilepsy characteristics in a large international cohort of patients with (likely) pathogenic ANKRD11 variants or deletions and to perform a genotype–phenotype analysis for the presence and type of epilepsy." (PMID 37501353, 2023). "In one family, three patients (p34, p35, and p36) had an identical ANKRD11 nonsense variant, but epilepsy was only present in two of them." (PMID 37501353, 2023). "Additionally, we included previously reported patients with (likely) pathogenic ANKRD11 variants and epilepsy from the literature." (PMID 37501353, 2023). "In total, eight patients had a chromosome 16q24.3 microdeletion including ANKRD11 among other genes, of whom six had epilepsy." (PMID 37501353, 2023). "Patients with a polygenic chromosome 16q24.3 microdeletion including ANKRD11 and epilepsy had a poorer cognitive outcome in comparison with patients with truncating variants and epilepsy, but findings were not significant, possibly due to low numbers." (PMID 37501353, 2023).
lymphoma (2 papers, 2018 to 2023). A malignant (clonal) proliferation of B- lymphocytes or T- lymphocytes which involves the lymph nodes, bone marrow and/or extranodal sites. "Seven gene mutations (Ankrd11, C130026I21 Rik, Gm10717, Gm10721, Gm11168, Muc4, and Zfp984) were hetero-/hemi-zygous in all three lymphomas and one gene (Itgav) had homozygous mutations in one lymphoma." (PMID 37145994, 2023).
Thrombocytopenia (2 papers, 2017 to 2021). A reduction in the number of circulating thrombocytes. "It is interesting that a paralog of ANKRD11, namely ANKRD26, is linked to thrombocytopenia inherited in a dominant manner and that ANKDR11 itself is expressed in bone marrow at high level." (PMID 28422132, 2017). "The single patient not deleted for ANKRD11, whose phenotype is characterized by milder psychomotor delay, cardiac congenital malformation, thrombocytopenia and astigmatism, confirms all this data." (PMID 28422132, 2017). "Interestingly, ANKRD11 itself is also expressed in bone marrow at a high level, but none of the 38 presented patients showed thrombocytopenia." (PMID 34604130, 2021).
Anosmia (1 paper, 2024). An inability to perceive odors. "Previously, one patient with 16q24.3 microdeletion, which encompasses ANKRD11, was reported to have anosmia." (PMID 38616269, 2024). "Since clinical phenotypes between patients with ANKRD11 variants vs 16q24.3 microdeletions may vary in nature, numbers, penetrance, and severity, it was not clear whether the anosmia in the 16q24.3 microdeletion patient was due to the deletion of ANKRD11 and/or any other genes." (PMID 38616269, 2024).
Chylothorax (1 paper, 2025). The presence of chyle in the thoracic cavity. "The newborn presented with KBGS complicated by chylothorax, attributable to a pathogenic variant in the ANKRD11 gene." (PMID 41230445, 2025). "Mechanistic insights into the functional loss of ANKRD11 may be elucidated by functional animal model studies how ANKRD11 dysfunction derails lymphatic development and leads to complications such as chylothorax." (PMID 41230445, 2025).
ciliopathies (1 paper, 2021). "Recently, Ankrd11 was directly associated with ciliopathies." (PMID 33996804, 2021).
COVID-19 (1 paper, 2024). A disease caused by infection with severe acute respiratory syndrome coronavirus 2. "The upregulation of ANKRD11 in neutrophils of COVID-19 patients following dexamethasone treatment has already been noted." (PMID 39012145, 2024).
Ewing sarcoma (1 paper, 2011). A small round cell tumor that lacks morphologic, immunohistochemical, and electron microscopic evidence of neuroectodermal differentiation. "A recent study that used a combined comparative genomic hybridization (CGH) and expression microarray analysis identified the ANKRD11 locus at 16q24.3 as one of the most frequently deleted and down-regulated genes in Ewing Sarcoma." (PMID 21197471, 2011).
focal dystonia (1 paper, 2025). A dystonia that is localized to a specific part of the body. "Because our patient’s movement disorder could be classified as a focal dystonia, the ANKRD11 gene should be added to the list of genes that can cause neurodevelopmental delay and transient movement disorders." (PMID 40760574, 2025).
growth disorders (1 paper, 2023). "All these variants were identified in genes already associated with growth disorders: PROKR2 (N = 2), PTPN11 (N = 6), ANKRD11 (N = 1), NPR2 (N = 1), NF1 (N = 1), ACAN (N = 1), GH1 (N = 1), FBN1 (N = 1), COMP (N = 1), IGF1R (N = 1), ARID1A (N = 1), and CASR (N = 1)." (PMID 37605180, 2023).
hepatocellular carcinoma (1 paper, 2016). A malignant tumor that arises from hepatocytes. "Six genes carrying DNVs were associated with human developmental disorders involving epithelial, connective or bone morphologies (PXDN, RTEL1, ANKRD11, MAP2K1, CYLD, ACAN) and four linked with cholangio- and hepatocellular carcinomas (PIK3CA, TLN1 CYLD, MAP2K1)." (PMID 27955658, 2016).
lymph node metastasis (1 paper, 2021). "In contrast, patients without lymph node metastasis were found to have more frequent mutation in four genes including GATA3, FOXA1, ANKRD11, and RET (P<0.05) and more CN amplifications in two genes including PIK3C2G and CCND2 (P<0.05)." (PMID 33968723, 2021).
medulloblastoma (1 paper, 2013). A malignant, invasive embryonal neoplasm arising from the cerebellum. "The N-terminal domain of the ANKRD11 was also reported as a nasopharyngeal carcinoma-susceptibility protein LZ16, and the central region of ANKRD11 was isolated as a tumor antigen present in childhood medulloblastoma." (PMID 23718802, 2013).
megacolon (1 paper, 2023). "Therefore, the clinical findings of congenital aganglionic megacolon in Pt 7 are likely related to decreased BDNF/TrkB signaling due to ANKRD11 deficiency caused by the deletion of exons 5–9 of the gene." (PMID 36564961, 2023).
myeloid malignancies (1 paper, 2017). "Most of the significantly mutated genes were previously well documented either in MDS or other myeloid malignancies, although some were newly identified or re-confirmed as recurrently mutated genes in our analysis, such as ROBO1/2, IHIT3, KIF20B, PTPRD, ANKRD11 and DHX9." (PMID 28220884, 2017).
Osteopenia (1 paper, 2016). Osteopenia is a term to define bone density that is not normal but also not as low as osteoporosis. "Homozygosity for a missense mutation in ANKRD11 is embryonic lethal in mice, whereas the heterozygous mice have an osteopenia-like phenotype and craniofacial abnormalities." (PMID 27900361, 2016).
persistent truncus arteriosus (1 paper, 2024). A rare congenital cardiovascular disorder characterized by the failure of the embryologic structure truncus arteriosus to divide into the aorta and pulmonary trunk. "We show that conditional knockout of Ankrd11 in the neural crest leads to a failure of AP septation by CNCCs, creating a cardiac defect termed persistent truncus arteriosus (PTA) and an associated VSD." (PMID 38951500, 2024).
Sepsis (1 paper, 2023). Sepsis is defined as life-threatening organ dysfunction caused by a dysregulated host response to infection. "As is known, KBGS is prone to be complicated by infectious diseases, so the patient’s intractable severe sepsis is speculated to be aggravated by the mutation of Ankrd11 gene." (PMID 37800809, 2023).
Turner syndrome (1 paper, 2022). Turner syndrome is a chromosomal disorder associated with the complete or partial absence of an X chromosome. "The pathogenic variants reported comprised one case of mosaic Turner syndrome (45,X) not detected on CMA, and four variants in the genes ARMC4, ANKRD11, GATA4 and NSD1, all of which would have been amenable to detection by whole exome sequencing in the PAGE and CUIMC studies." (PMID 34411415, 2022).
neurodevelopmental disorder (13 papers, 2017 to 2025). A behavioral and cognitive disorder with onset during the developmental period that involves impaired or aberrant development of intellectual, motor, or social functions. "ANKRD11 is one of the most frequently de novo mutated genes in monogenic neurodevelopmental disorders (NDDs) and is moderately de novo mutated in autism spectrum disorder (ASD)." (PMID 38616269, 2024). "ANKRD11 is one of the most disrupted genes in monogenic neurodevelopmental disorders with de novo mutations." (PMID 33996804, 2021). "Mutations in ANKRD11, ATP6AP2 and PRPS1 have also been associated with several neurodevelopmental disorders with ID in humans." (PMID 36551904, 2022). "In addition, some researchers suggest that ANKRD11 gene variation should be classified as a neurodevelopmental disorder and belong to the category of chromatin disease because the phenotypes of KBGS, CdLS, and Coffin–Siris syndrome (CSS) overlap greatly." (PMID 35330407, 2022).
tumor (13 papers, 2009 to 2025). "Integrated WGS and tNGS analysis clearly distinguished this tumor type from EBV-negative DLBCL due to frequent mutations in ARID1A (45%), KMT2A/KMT2D (32/30%), ANKRD11 (32%), or NOTCH2 (32%)." (PMID 34039950, 2021). "All of these showed ANKRD11 is a putative tumour-suppressor gene." (PMID 23718802, 2013). "The results show that ANKRD11 may be a tumor suppressor gene." (PMID 34604130, 2021). "SETD1A knockdown changed the landscape of SEs, resulting in activation of the transcription of SE-driven tumor suppressors, such as ST3GAL4, AKAP12, PTPN1, AQP9, and ANKRD11." (PMID 37581938, 2023). "On the other hand, 3 genes (ANKRD11, BCL11A, and FOXN3) out of the top 5 mythelated genes in cluster 6 are well-known in their anti-tumor action." (PMID 32272578, 2020). "On the other hand, four genes (ANKRD11, PHLDA3, APOL1 and MSX1) are known as tumour-suppressor factors." (PMID 19826427, 2009).
cancer (10 papers, 2009 to 2024). A tumor composed of atypical neoplastic, often pleomorphic cells that invade other tissues. "Mutations in the gene ankyrin repeat domain containing 11 (ANKRD11/ANCO1) play a role in neurodegenerative disorders, and its loss of heterozygosity and low expression are seen in some cancers." (PMID 37511268, 2023). "We identified 35 genes that were more frequently altered in HS/CB tumors versus corresponding TCGA cohorts; of which, 8 genes (PREX2, BIRC6, CNTNAP2, PTPRB, GRM3, ANKRD11, BRCA2, and TET3) are listed on the OncoKB Cancer Genes catalogue." (PMID 34446728, 2021). "In the present study, the smoking-related methylation changes to RUNX3, IL6R, PTAFR, and ANKRD11 (cardiovascular-related genes) and CEP135 and CDH23 (cancer-related genes) corresponded to increased gene expression." (PMID 26756918, 2016). "However, considering the characteristics of SP cells for cancer-initiating ability, the apoptosis-related molecules among these genes (MCL-1, ANKRD11, PHLDA3 and APOL1) might have roles in the proliferation of SP cells." (PMID 19826427, 2009).
movement disorder (2 papers, 2024 to 2025). Neurological conditions resulting in abnormal voluntary or involuntary movement, which may impact the speed, fluency, quality and ease of movement. "To date, only one case of a movement disorder in association with an ANKRD11 variant has been described." (PMID 39346806, 2024).
cardiovascular diseases (1 paper, 2016).
kidney disease (1 paper, 2017). "Thus, our study confirms some of the previously reported kidney disease associated CpGs including ANKRD11 at epigenome-wide significance, while discovering and replicating 18 additional loci." (PMID 29097680, 2017).
neurological disorders (1 paper, 2023). "ADAM23, ANKRD11, and MACROD2 function in the nervous system and are associated with several neurological disorders." (PMID 37805653, 2023).
ANKRD11 also shares sentences with these, for which no sentence is quoted: autism spectrum disorder (6 papers); genetic disorder (4); CHOPS syndrome (2); infection (2); microcephaly (2); 22q11.2 deletion syndrome (1); Alpha-thalassemia (1); Aortic Valve Disease 1 (1); asthma (1); Astigmatism (1); atherosclerosis (1); B-cell lymphoma (1); Beals syndrome (1); brain diseases (1); Camptodactyly (1); Cardiac-urogenital syndrome (1); chronic atrial and intestinal dysrhythmia syndrome (1); cleft palate (1); colorectal carcinoma (1); congenital heart disease (1); craniosynostosis (1); dyslipidemia (1); Dystonia (1); Floating-Harbor syndrome (1); hydrops (1); Hypertelorism (1); Hypertension (1); infectious disease (1); memory impairment (1); metabolic disorders (1).
A further 18 diseases each share a sentence with ANKRD11 in 1 paper.